PRDM8 (PR/SET domain 8)
Description:
Probable histone methyltransferase, preferentially acting on 'Lys-9' of histone H3 (By similarity). Involved in the control of steroidogenesis through transcriptional repression of steroidogenesis marker genes such as CYP17A1 and LHCGR (By similarity). Forms with BHLHE22 a transcriptional repressor complex controlling genes involved in neural development and neuronal differentiation (By similarity). In the retina, it is required for rod bipolar and type 2 OFF-cone bipolar cell survival (By similarity).
Synonyms: PFM5; KMT8D; EPM10
Tractability: No criterion of Open Targets' tractability assessment is met for any kind of drug.
Target class: Enzyme; Transferase
Gene: Protein-coding gene on chromosome 4 (80,183,879 to 80,204,329, forward strand). Ensembl gene ENSG00000152784.
Subcellular location: Nucleus
Subcellular location (Human Protein Atlas): Nuclear bodies; Nucleoplasm
Pathways (Reactome):
Cell-Cell communication: Regulation of CDH11 gene transcription
Gene Ontology:
Molecular function: protein binding; chromatin binding; histone H3K9 methyltransferase activity; histone methyltransferase activity; transcription corepressor activity
Biological process: regulation of DNA-templated transcription; chromatin remodeling; negative regulation of DNA-templated transcription
Cellular component: nuclear body; nucleoplasm; nucleus
Genetic constraint (gnomAD): Loss-of-function variants: 13 observed, 41.46 expected, observed/expected ratio (o/e) 0.31, 90% interval 0.2 to 0.5. The synonymous counts are far from expectation, so gnomAD's model fits this gene poorly and the ratio says little. Missense variants: 998 observed, 883.8 expected, observed/expected ratio (o/e) 1.13, 90% interval 1.07 to 1.19. Synonymous variants: 473 observed, 398.43 expected, observed/expected ratio (o/e) 1.19, 90% interval 1.1 to 1.28.
Homologues: Orthologues: chimpanzee PRDM8 (99% identical), macaque PRDM8 (99% identical), pig PRDM8 (90% identical), mouse Prdm8 (89% identical), dog PRDM8 (88% identical), rat Prdm8 (87% identical), guinea pig PRDM8 (66% identical), tropical clawed frog prdm8 (57% identical), zebrafish prdm8b (55% identical), Drosophila melanogaster CG13287 (17% identical). Paralogues in human: ZNF488 (15% identical).
Diseases named in the same sentence as PRDM8 in open-access papers:
PRDM8 is named in the same sentence as 37 diseases in open-access papers, as found by Europe PMC text mining. Sharing a sentence is not in itself a finding about the gene and the disease. The quoted sentences say what the papers report.
Down syndrome (5 papers, 2016 to 2023). "Moreover, we found differentially methylated probes within ITGA9 and ADAM12 genes, whose methylation is altered in systemic sclerosis, and within the PRDM8 gene, whose methylation is affected in dyskeratosis congenita and Down syndrome." (PMID 28861129, 2017). "Aberrant DNA methylation was observed in the gene PRDM8 in DKC and AA as well as in other diseases with premature aging phenotype, such as Down syndrome and Hutchinson-Gilford-Progeria syndrome." (PMID 32819411, 2020). "This is of particular interest, as PRDM8 is hypermethylated in DKC, aplastic anaemia (AA) and Down syndrome, although in a different region (spanning from the CpG island chr4:81118137-81118603 to the CpG island chr4:81119095-81119391)." (PMID 28861129, 2017).
bone marrow failure syndrome (2 papers, 2016 to 2020). "Aberrant hypermethylation is particularly observed in PRDM8 and this may support identification and classification of bone marrow failure syndromes." (PMID 26909595, 2016). "Furthermore, aberrant DNA methylation in PRDM8 provides another biomarker for bone marrow failure syndromes and modulation of this gene in cellular subsets may be related to the hematopoietic and neuronal phenotypes observed in premature aging syndromes." (PMID 32819411, 2020). "Therefore, analysis of epigenetic age or aberrant DNA methylation in PRDM8 might be advantageous in patients without significant telomere attrition or specific mutations to identify these bone marrow failure syndromes." (PMID 32819411, 2020).
depression (2 papers, 2022 to 2025). "Additionally, BHLHE22 forms a repressor complex with the PRDM8 protein, whose protein-protein interaction site is not yet understood and may overlap with this association with severe depression." (PMID 34664540, 2022).
essential hypertension (2 papers, 2020 to 2022). Hypertension that presents without an identifiable cause. "The SNPs we report near PRDM8/FGF5 on chromosome 4 showed pleiotropic risk associations with essential hypertension and severe depressive episode with psychotic symptoms." (PMID 35701404, 2022). "Systematic studies have identified a positive link between altitude (and thus hypoxia) with the frequency of hypertension in humans and PRDM8 belongs to a family of histone methyltransferases that are known as negative regulators of transcription." (PMID 32616020, 2020).
hepatocellular carcinoma (2 papers, 2021 to 2023). A malignant tumor that arises from hepatocytes. "PRDM8 is also a strong tumor suppressor that is downregulated in hepatocellular carcinoma; thus, loss of peaks at this locus supports an analogous role in JMML onset." (PMID 37958378, 2023).
premature ageing syndromes (2 papers, 2017 to 2020). "Since DKC is one of various prominent premature aging syndromes, we subsequently analyzed if PRDM8 is also aberrantly methylated in other premature aging syndromes." (PMID 32819411, 2020). "Furthermore, aberrant hypomethylation within the promoter region of the longer of the two PRDM8 transcripts (NM_020226.3) was observed in all premature aging syndromes, albeit this was less prominent in DKC and Werner syndrome." (PMID 32819411, 2020). "This may indicate that aberrant regulation of PRDM8 may contribute to impaired neurological development, which is characteristic for many premature aging syndromes." (PMID 32819411, 2020). "Furthermore, DKC and AA revealed aberrant DNA methylation within the gene PRDM8, which was also observed for other premature aging syndromes." (PMID 32819411, 2020). "However, the PRDM8 gene resulted hypermethylated in both WS and DKC, although in different CpG sites, suggesting that epigenetic remodelling in different premature ageing syndromes can converge on the same gene." (PMID 28861129, 2017).
progressive myoclonic epilepsy-10 (2 papers, 2020 to 2022). "Genetic studies have observed association of PRDM8 with progressive myoclonic epilepsy-10." (PMID 32475352, 2020).
Ataxia (1 paper, 2023). Ataxia refers to impaired coordination of voluntary muscle movement. "A subset of FS symptoms, such as dystonia, myoclonus, and ataxia, may be attributed to the downregulation of PLEKHG2, DST, ARX, AAAS, KCTD17, PRDM8, and CRTC1 in FS brains as these genes are downregulated in Q84Pfs-Het brains and play a role in these movement and muscle coordination 43–49." (PMID 37398410, 2023).
atrial fibrillation (1 paper, 2022). A disorder characterized by an electrocardiographic finding of a supraventricular arrhythmia characterized by the replacement of consistent P waves by rapid oscillations or fibrillatory waves that vary in size, shape and timing and are accompanied by an irregular ventricular response. "The second most pleiotropic SNP (rs1458038) is mapped to the PRDM8 gene that is implicated in affecting blood pressure, atrial fibrillation, apolipoprotein B levels, LDL cholesterol levels." (PMID 36579561, 2022).
breast carcinoma (1 paper, 2015). "We found that for seven HMTs (KMT2C, SETDB2, SETD2, SETMAR, PRDM1, PRDM5, and PRDM8), copy number amp/gain or deletion was significantly associated (p<0.05) with shorter survival in breast cancer patients." (PMID 25537518, 2015).
embryonal carcinoma (1 paper, 2014). A non-seminomatous malignant germ cell tumor characterized by the presence of large germ cells with abundant cytoplasm resembling epithelial cells, geographic necrosis, high mitotic activity, and pseudoglandular and pseudopapillary structures formation. "In the P19 embryonal carcinoma cell line, we found a gradual increase in the Prdm8 mRNA level with neural differentiation after the treatment with retinoic acid, and this increment was almost coincident with the expression of post-mitotic neuronal markers (data not shown)." (PMID 24489718, 2014).
hemorrhagic disease (1 paper, 2021). Spontaneous or near spontaneous bleeding caused by a defect in clotting mechanisms (blood coagulation disorders) or another abnormality causing a structural flaw in the blood vessels (hemostatic disorders). "Most of these genes are known to be involved in the manifestation of various clinical phenotypes, such as metabolic diseases (CPT1B and BLVRA); hemorrhagic diseases (RUNX1 and GP6); and neuronal disorders (KCNAB3, FAM179B, CCDC60, GRM6, and PRDM8), among others." (PMID 34440289, 2021).
Lafora body disease (1 paper, 2017). "Two genes are associated with Lafora disease; EPM2A (laforin) and EPM2B (malin) and a third gene PRDM8 that is associated with an early onset variant of Lafora body disease has been described." (PMID 27718144, 2017).
Merkel cell carcinoma (1 paper, 2020). "Next, we were interested in investigating upstream regulators of PRDM8 in Merkel cell carcinoma." (PMID 32344701, 2020). "This study reports the role of PRDM8 in virus-negative Merkel cell carcinoma." (PMID 32344701, 2020).
tumor (7 papers, 2011 to 2023). "Recent studies on HCC showed that PRDM8 suppresses the occurrence of tumor via interacting with NAP1L1." (PMID 34368121, 2021). "We also demonstrated the role of PRDM8 in the tumor cell proliferation and clonogenicity in VN-MCC using the CRISPR-mediated loss-of-function assay and validated the dependency between the expression level of PRDM8 and H3K9me3." (PMID 32344701, 2020). "This can shed light on the PRDM8 mechanism of action by possibly silencing tumor suppressors through the recruitment of repressive histone mark H3K9me3." (PMID 32344701, 2020). "We further investigated the mechanism by which PRDM8 is regulated in this type of tumor that differentiates VN-MCC from VP-MCC tumors, and lastly the mechanism by which it acts in VN-MCC." (PMID 32344701, 2020). "Heterogeneity in the mutation frequencies was observed in the different tumor types with higher mutation rates found for PRDM3/MECOM, PRDM8, PRDM9, PRDM15, ZFPM1/FOG1 and ZFPM2/FOG2 in specific cancers." (PMID 30347759, 2018). "In HCC, NAP1L1 acts as a tumor promoter and is repressed by PRDM8 and let-7c-5p." (PMID 34368121, 2021). "We show higher expression levels of PRDM8 in VN-MCC cells as well as patient tumor samples." (PMID 32344701, 2020). "Our findings in this study indicating PRDM8-induced increase in trimethylation of histone H3K9 might support this notion by playing a role in silencing tumor suppressor genes." (PMID 32344701, 2020). "In addition, three genes common to both patients which carried bivalent marks in normal and lost H3K4me3 in tumor, LHX9, PKNOX2 and LBXCOR1 and one, PRDM8, lost the H3K27me3 in tumor, all of which are transcription factors with unknown function in colon." (PMID 22011431, 2011). "SMYD2, EZH2, and SUV420H2 were up‐regulated and SETD7, PRDM1, PRDM8, PRDM6, and PRDM5 were down‐regulated in tumor." (PMID 30984543, 2019). "Of note, TCGA gene expression profiling of PRDM genes revealed significant overexpression of PRDM12 and PRDM13 in many tumor types whereas ZFPM2/FOG2, PRDM8, and PRDM16 were more often downregulated in tumor tissues." (PMID 30347759, 2018). "To investigate whether patient tumor samples recapitulated a similar pattern as in MCC cells, we analyzed five tumors from each MCC subtype for their PRDM8 expression." (PMID 32344701, 2020).
cancer (5 papers, 2018 to 2024). A tumor composed of atypical neoplastic, often pleomorphic cells that invade other tissues. "In detail, PRDM8 and PRDM15 were mutated at low rates in most of the analyzed cancer types except PAAD where they were both frequently mutated (16.0% and 11.2%, respectively)." (PMID 30347759, 2018). "In this study, OncodriveCLUST analysis revealed two putative cancer mut-driver genes: PRDM8 in PAAD and ZFPM1/FOG1 in ACC." (PMID 30347759, 2018). "We also observed somatic variants in several known cancer-associated genes (for example, JAG1, PRDM2, PRDM8, SETD2, ASPM, ZIC, GRIK1, etc.), which may be important for cell growth and proliferation." (PMID 30871634, 2019). "MEGM DEGs are mainly associated with the topics ‘cancer’, ‘neuro’ and ‘eye & retina’ or two combined topics like ‘cancer and neuro’ (SEMA3C, ROR1, EPHA7, GDNFR) or ‘eye & retina and neuro’ (PRDM8, CRYBG3)." (PMID 39695086, 2024). "Based on the scores of this analysis, ZFPM1/FOG1 can be considered as a cancer driver for ACC and PRDM8 for PAAD." (PMID 30347759, 2018). "However, the mRNA expression levels of PRDM1, PRDM2, PRDM8, and PRDM11 were higher in normal and cancer tissues." (PMID 39468462, 2024).
PRDM8 also shares sentences with these, for which no sentence is quoted: dyskeratosis congenita (2 papers); Hutchinson-Gilford progeria syndrome (2); pituitary adenomas (2); Werner syndrome (2); aplastic anaemia (1); Borderline personality disorder (1); Coffin-Siris syndrome (1); Dystonia (1); Hypertension (1); Leber congenital amaurosis 11 (1); leukemia (1); lung carcinoma (1); metabolic disease (1); microcephalic osteodysplastic primordial dwarfism type II (1); microphthalmia (1); multiple sclerosis (1); nasopharyngeal carcinoma (1); psychiatric disorder (1); systemic sclerosis (1); uterine corpus endometrial carcinoma (1); ventricular septal defect 2 (1).